MTOR (mechanistic target of rapamycin kinase)
Diseases named in the same sentence as MTOR in open-access papers (continued):
Sharing a sentence is not in itself a finding about the gene and the disease.
breast cancer (continued). "The activation of mTOR was accompanied by decreased expression of GAS5 and PTEN (mediated by miR-21), leading to an increase in the resistance of breast cancer patients to trastuzumab." (PMID 34202777, 2021). "Rhaponticin was also validated to inhibit the expression of fatty acid synthase in breast cancer and the PI3K/AKT/mTOR pathway in osteosarcoma." (PMID 34575983, 2021). "This review focuses on roles of miRNAs in breast cancer progression, particularly their involvement in Wnt/β-catenin, Notch, PI3K/AKT/mTOR, BMI-1 and STAT3 pathways in breast cancer stem cells (BCSCs)." (PMID 33413418, 2021). "It was reported that mTOR signaling is dysregulated in breast cancer patients following abemaciclib treatment and PI3K/mTOR pathway has been shown to be upregulated in response to chronic exposure to CDK4/6 inhibitors." (PMID 34123801, 2021). "GAS5 is also a key player in the regulation of some crucial signal pathways in breast cancer, such as PI3K/AKT/mTOR, Wnt/β-catenin, and NF-κB signaling." (PMID 34202777, 2021). "Our correlation analysis revealed that EGFR expression was strongly correlated with expressions of mTOR (r= 0.262–0.496) and FGFR1 (r= 0.203–0.348) in liver, lung, kidney, glioblastoma, colon, head and neck, and breast cancers." (PMID 33842373, 2021). "In a mouse model of breast cancer, inhibition of DPP-4 promoted metastasis formation, while metformin had an inhibitory effect on it by influencing mTOR-related signals." (PMID 34778040, 2021). "In PI3K-addicted HER2(+) breast cancers, a four-drug combination targeting HER2 along with PI3K, AKT, and mTOR successfully blocked tumor cell proliferation." (PMID 34461089, 2021). "Curcumin also sensitizes MDR breast cancer cells to cisplatin treatnment and activates autophagy by suppressing the PI3K/AKT/mTOR pathway." (PMID 34575981, 2021). "In conclusion, our study proved that HHT suppressed breast cancer cells proliferation, migration and induced apoptosis through miR-18a-3p/AKT/mTOR signaling pathway." (PMID 33867824, 2021). "Interestingly, the fusion genes identified by analyzing breast cancer genome rearrangements indicated that ErbB2 might serve as an adaptor for DEPTOR in regulating the mTOR pathway 25, thus adding another layer of complexity in the cross-talk between DEPTOR and ErbB2 in breast tumorigenesis." (PMID 33995662, 2021). "Dephosphorylation of Akt and increased expression of PTEN by statin treatment is also reported to suppress PI3K/Akt/mTOR pathway in ER-positive (MCF-7, T47D) as well as ER-negative (MDA-MB-231) breast cancer cells." (PMID 34603386, 2021). "Activation of the PI3K/PTEN/AKT/mTOR pathway promotes invasion and metastasis by increasing the expression of MMP9 in hepatocellular carcinoma cells and human breast cancer cells." (PMID 34335799, 2021). "TQ inhibits the metastasis of renal cell cancer cells, breast cancer cells and human renal carcinoma cells by inducing autophagy via the generation of ROS and the activation of the AMPK/mTOR signaling pathway." (PMID 34575981, 2021). "Although attenuation of ERK signal was only seen in ER- breast cancer cells, it is interesting that CSNK1G2 can target both PI3K/AKT/mTOR/S6K and ERK signal pathways depending on the characteristics of hormone receptor subtypes." (PMID 33861751, 2021). "In metastatic breast cancer cells, PI3K, Akt, mTOR, and RhoA were demonstrated to be responsible for migration regulation by CERK." (PMID 33430896, 2021). "Previous studies from our lab have shown that RE inhibits the phosphorylation/activation of mTOR in PC-3 prostate cancer cells, MDA-MB-231 breast cancer cells, and A549 NSCLC cells." (PMID 35054445, 2021).
breast cancer (continued). "Here, we confirmed new strategies in both HER2+ breast cancer and TNBC cell lines, not only by using the on-target effect of ERBB family protein inhibition but also by suppressing the compensatory PI3K-Akt-mTOR and MAPK pathways." (PMID 34203351, 2021). "The luteolin suppresses Akt/mTOR axis to reduce MMP-9 expression, impairing metastasis and invasion of breast cancer cells." (PMID 34769099, 2021). "We found that TMEM176B expression on breast cancer cells was important for cell proliferation and migration, AKT/mTOR signaling, and the regulation of a number of genes involved in angiogenesis, KRAS signaling, EMT, and estrogen and interferon responses." (PMID 34943938, 2021). "It has also been reported that caryophyllene oxide inhibits cell growth in human prostate and breast cancer cells by inducing apoptosis and suppressing the PI3K/AKT/ mTOR/S6K1 pathways." (PMID 33129236, 2021). "The CK1 inhibitor, D4476, partly mimicked the CSNK1G2 knockdown effect in ER+ breast cancer cells, but with a broader repression ranging from PI3K/AKT/mTOR/S6K to ERK signaling." (PMID 33861751, 2021). "Radiation also induces the activation of the PI3K/AKT signaling pathway in breast cancers and targeting this pathway by the dual PI3K/mTOR inhibitor NVP-BEZ235 sensitizes the MDA-MB231 and MCF7 breast cancer cells to IR." (PMID 34217266, 2021). "In breast cancer, gedatolisib (PF-05212384) is a dual PI3K/mTOR inhibitor that was evaluated in combination with either docetaxel, cisplatin, or dacomitinib in triple-negative breast cancer (NCT01920061)." (PMID 34298731, 2021). "Hyperactivation of the PI3K/AKT/mTOR cell signalling pathway is an important and well-described mechanism of trastuzumab resistance in HER2-positive breast cancer." (PMID 34204960, 2021). "In breast cancer cells, SALL2 silencing activated the AKT/mTOR pathway via the downregulation of PTEN." (PMID 34944911, 2021). "We have recently reported that metformin mitigates DPP-4 inhibitor-induced breast cancer EMT and metastasis via the suppression of mTOR activation." (PMID 34063285, 2021). "The mTOR pathway activation gene signature is also enriched in MLL3 KD and mutant breast cancer samples compared to WT." (PMID 34581028, 2021). "Further clinical studies to evaluate combinations of hormone therapy with PI3K, AKT, mTOR, or CDK 4/6 inhibitors, together with clinical trials in other breast subtypes, are still ongoing and will lead to improved therapies to treat breast cancer patients." (PMID 34298731, 2021). "In this study, we clarify that COL17 overexpression suppresses the cell proliferation and growth of breast cancer and attenuates the AKT/mTOR signaling molecules." (PMID 34293053, 2021). "For the molecular mechanisms in breast cancer, metformin activates AMP-activated protein kinase (AMPK) and leads to the inhibition of mTOR signaling and protein synthesis, which is responsible for the cancer cell proliferation." (PMID 33431790, 2021). "By combining abemaciclib with a PI3K inhibitor, three pathways (Akt, PIM, and CDK4) to mTOR activation are neutralized, suggesting a potential combination strategy for the treatment of PIK3CA-mutant ER+ breast cancer." (PMID 32391118, 2020). "CC-115, a dual inhibitor of mTOR and DNA-PKcs, has been shown to inhibit cell growth in vitro by blocking DDR pathways, thus inducing apoptosis in many cancer lines, including breast cancer cells." (PMID 32211045, 2020). "Previous studies have found that FKBP4 can interact with PI3K in breast cancer and activate Akt through PDK1 and mTORC2, thereby activating the Akt/mTOR signaling pathway." (PMID 33354489, 2020). "The oncogenic roles of AKT1S1 have been reported in colon cancer, liver cancer, lung cancer, prostate cancer, breast cancer, and so on via regulating PI3K/Akt, mTOR, and/or NF-κB signaling pathways." (PMID 32656205, 2020).
breast cancer (continued). "Several approaches to targeting the PI3K/AKT/mTOR pathway have been shown to be effective in metastatic oestrogen receptor-positive, HER2-negative breast cancer in combination with endocrine therapy." (PMID 32035020, 2020). "Taken together, we showed that actein exhibited significant anti-metastasis activity through the modulation of AKT/mTOR and Ras/Raf/MAPK signaling pathway in HER2-positive breast cancer cells in vitro." (PMID 32547952, 2020). "Our in vivo assessment of IBL-302 in subcutaneous xenograft models also shows that the PIM/PI3K/mTOR inhibitor, IBL-302, is effective in in vivo models of HER2+ breast cancer." (PMID 32042115, 2020). "For example, PI3K/Akt/mTOR pathway-mediated stimulation of HIF-1 mRNA translation through the activation of two downstream targets of mTOR, p70SK6, and 4E-BP1 in breast cancer cells has been observed." (PMID 32252351, 2020). "AA also inhibited breast cancer growth and breast cancer‐induced bone osteolysis by reducing osteoclast formation and function and inactivated PI3K/AKT/mTOR signaling in vivo." (PMID 32976685, 2020). "Western blot assays further illustrated that Rg5 decreased the phosphorylation levels of PI3K, Akt, mTOR, and Bad and suppressed the PI3K/Akt signaling pathway in breast cancer." (PMID 31963684, 2020). "Given the published roles of PI3K/AKT/mTOR, and more recently of PIM kinase signalling in mediating resistance to HER2- targeted therapies, we evaluated IBL-302 in breast cancer models of acquired trastuzumab and lapatinib resistance." (PMID 32042115, 2020). "We found that the activation phosphorylation of PI3K, AKT, and mTOR was significantly decreased after AA treatment in MDA‐MB‐231 and MDA‐MB‐436 breast cancer cells." (PMID 32976685, 2020). "Everolimus is a mammalian target of rapamycin (mTOR) inhibitor approved by the FDA for use in advanced RCC, PNET, and breast cancer." (PMID 32927828, 2020). "Of the breast cancer cell lines evaluated, MCF7 cells expressed higher levels of phosphorylated and endogenous mTOR and S6K1." (PMID 31959810, 2020). "In this study, we investigated the mechanism of a dual PI3K and mTOR inhibitor, DHW-208 on the growth of breast cancer cells both in vitro and in vivo." (PMID 32606352, 2020). "We previously identified the mTOR pathway components RHEB and RPTOR as being positively regulated by EVI1 in metastatic breast cancer with stem cell-like features." (PMID 32012804, 2020). "In breast cancer, overexpressed XCR1 inhibits cell growth and tumorigenesis via suppression of the MAPK and PI3K/AKT/mTOR signaling pathways." (PMID 33374849, 2020). "We found that the phosphorylated and endogenous levels of mTOR and S6K1 were generally increased in breast cancer cells compared to those of normal breast MCF10A cells." (PMID 31959810, 2020). "It has been shown that curcumin inhibits mammalian target of rapamycin (mTOR)—a serin/threonine kinase—and downregulates the key epigenetic regulator enhancer of zeste homolog 2 (EZH2) in tamoxifen resistant breast cancer cells." (PMID 31936346, 2020). "Mammalian target of rapamycin (mTOR) is a downstream effector of the PI3K-Akt pathway, and its activity in breast cancer has been shown to mediate resistance to PI3K inhibition." (PMID 32399646, 2020). "In this study, the pan-PIM, PI3K and mTOR inhibitor, IBL-302, demonstrated efficacy across 40 breast cancer cell lines with GI50s ranging from 36 nM (MDA-MB-361) to 2656 nM (BT-483)." (PMID 32042115, 2020). "Previous research reported that among its potential anti-tumor actions in breast cancer, DMC targeted multiple AMPK downstream pathways involving dephosphorylation of Akt and mTOR inhibition." (PMID 33221748, 2020). "Our results in MCF-7 breast cancer cells demonstrate that HT decreases HIF-1α protein, probably by downregulating oxidative stress and by inhibiting the PI3K/Akt/mTOR pathway." (PMID 32286485, 2020).
breast cancer (continued). "Silencing BAG1 in breast cancer cells increases resistance to tamoxifen and reduces apoptosis by activating the PI3K/Akt/mTOR signaling pathway, and the overexpression of ATG16L2 is related to poor prognosis in epithelial cancer." (PMID 32547955, 2020). "Biochemical analysis reveals, in addition to previously reported activation of PI3-kinase/Akt/mTOR pathway, PRR14 overexpression regulates cell cycle in breast cancer by inhibiting CHEK2’s activation, followed with the deregulation of DNA damage pathway." (PMID 32541902, 2020). "So far, another dual mTOR inhibitor, MLN0128 is used only in vitro on cell models against everolimus-resistant breast cancer, and it inhibits the AKT phosphorylation." (PMID 33375317, 2020). "Meanwhile, enhanced IRE1 activity has been demonstrated to increase the production of protumorigenic cytokines in breast cancer cells to survive paclitaxel, and ATF6 is required to promote mTOR activation and STAT3 signaling to gain chemoresistance." (PMID 33396303, 2020). "Suppressed autophagy on the account of miR-101 is reported in breast cancer (targeting RAB5A, STMN1 and ATG4D), HCC (through EZH2) and in ischemic liver (via activating mTOR signaling pathway)." (PMID 32124227, 2020). "To re-evaluate the clinical impacts of the PI3K/AKT/mTOR pathway on anti-HER2 therapy pathway, we conducted a retrospective analysis using clinical data from patients with HER2+ breast cancer who had received anti-HER2 therapies." (PMID 33303839, 2020). "Collectively, our study is the first to document the oncogenetic role of PRR14 in breast cancer, which protects cells from apoptosis and stimulates proliferation by activating the PI3-kinase/Akt/mTOR pathway and inhibiting the CHEK2 pathway." (PMID 32541902, 2020). "For example, in NMuMG breast cancer cells TGFβ stimulated AKT and activated downstream effectors mTOR, P70S6K, and 4E-BP1, leading to increased cell size and proliferation that were associated with EMT." (PMID 33150300, 2020). "First, we determined the expression levels of phosphorylated-mTOR (p-mTOR), a direct upstream regulator of S6K1, and p-S6K1 in normal breast cells and several breast cancer cell lines." (PMID 31959810, 2020). "In the current study, Rg5 reduced the phosphorylation of PI3K, Akt, mTOR, and Bad, which suggested that Rg5 suppressed the PI3K/Akt pathway in breast cancer cells." (PMID 31963684, 2020). "The main objective in this research was to evaluate by using in silico study the carvacrol on HER2, PI3Kα, mTOR, hER-α, PR, and EGFR receptors involved in breast cancer progression by docking analysis, molecular dynamic, and drug-likeness evaluation." (PMID 33163084, 2020). "Studies suggest that metformin inhibits mammalian target of rapamycin (mTOR)-dependent and independent AMP-activated protein kinase (AMPK) activation in breast cancer or GC cells." (PMID 32717852, 2020). "In basal-type breast cancer, the Tumor Genome Atlas showed in basal-type breast cancer that the PI3K/AKT/mTOR-signaling pathway was frequently activated." (PMID 32153503, 2020). "The authors showed that ionizing radiation increases both mTOR signalling and subsequent p-S6K1 levels in breast cancer cells." (PMID 31959810, 2020). "DHW-208 remarkably suppressed the activation of AKT, mTOR, p70S6K, and 4EBP1 in breast cancer cell T47D and MDA-MB-231, thus inhibited PI3K/Akt/mTOR pathway." (PMID 32606352, 2020). "Corroborated, these results exhibit the key role played by mTOR inhibitors, especially by everolimus, in the treatment of ER positive/HER2 positive breast cancers with endocrine resistance." (PMID 33375317, 2020). "Identification of cytoplasmic biologic markers in breast cancers, which are proteins that run in the PUKCA/AKT/mTOR pathways, such as PIK3CA, PTEN, pAKT/pS6, metabolites, and aldehyde dehydrogenase 1 (ALDH1), is being widely developed." (PMID 32695508, 2020).
breast cancer (continued). "To date, many therapeutic targets have been verified for treating breast cancers, including CDK4/6 inhibitors, HDAC inhibitor, Estrogen pathway antagonists, VEGF inhibitors, PI3K inhibitors, mTOR inhibitors, etc.6–8." (PMID 32606352, 2020). "Because of its important role in the PI3K/Akt/mTOR signaling pathway, mTOR and downstream HIF-1α have been experimentally suggested to be inhibited by miR-99a, which reverses the breast cancer stem cell malignant phenotype." (PMID 32014012, 2020). "We thus believe that the novel PIM and PI3K/mTOR inhibitor, IBL-302, represents an exciting new potential treatment option for breast cancer, and that it should be considered for clinical investigation." (PMID 32042115, 2020). "In this study, we investigated the synergistic effects of sirolimus (anti-mTOR) and sunitinib (multi-targeted receptor tyrosine kinase inhibitors) on NMU-induced breast cancer." (PMID 33112549, 2020). "In this study, we demonstrated that PIK3CA mutations, which lead to constitutive activation of the PI3K/AKT/mTOR pathway, play important roles in resistance against HER2 monotherapy in breast cancer cell lines." (PMID 33303839, 2020). "This crosstalk and the convergence of PIM and Akt on mTOR signaling led us to test the combination of BYL719 and abemaciclib in breast cancer cells, where we observed synergistic inhibition of cell growth and attenuation of downstream signaling." (PMID 32391118, 2020). "The relevance of dually targeting mTOR and HDAC to prevent mitotic progression has also been demonstrated on other tumor entities such as prostate, ovarian, and mammary carcinoma." (PMID 32512849, 2020). "Further studies have revealed that C/EBPδ inhibited the expression of FBXW7, thereby increasing the activities of the FBXW7 substrates such as mTOR and HIF-1α and potentiated metastasis in mammary tumors." (PMID 30791487, 2019). "In summary, our data show that ADAM15 expression in breast cancer cells leads to upregulated expression of the tight junction protein Claudin-1, which involves activation of the PI3K/mTOR pathway." (PMID 31467400, 2019). "MicroRNA-10a is an inhibitor of breast cancer progression, promoting apoptosis in MCF-7 cells, via PI3K/Akt/mTOR." (PMID 31331001, 2019). "Inhibition of Akt phosphorylation, mTOR and Bcl2 along with increased BAX expression and caspase 3 cleavage are also involved in mediating apoptosis in curcumin treated breast cancer cells." (PMID 31618928, 2019). "By studying several autophagic markers and events in human breast cancer SKBR-3 cells, we further demonstrated that ITM2A is a novel positive regulator of autophagy through an mTOR-dependent manner." (PMID 31438969, 2019). "Forced expression of FAM83D in nonmalignant cells in culture promoted proliferation and invasion of breast cancer cells and down-regulated the expression of F-box and WD repeat domain-containing 7 (FBXW7), a suppressor of c-Myc, mTOR and C-Jun expression." (PMID 30910840, 2019). "The PI3K/AKT/mTOR pathway has been shown to play significant roles in the development, progression, and metastatic of TNBC breast cancer." (PMID 30713576, 2019). "Everolimus, an mTOR inhibitor, is approved and has demonstrated activity in combination with exemestane in hormone receptor-positive, HER2-negative breast cancer." (PMID 30915162, 2019). "It inhibits the proliferation of cells with PI3K/AKT/mTOR pathway alterations at submicromolar IC50 values and showed its highest activity in luminal breast cancer cell lines." (PMID 31835495, 2019). "The aim of this study was to interrogate IF as a predictive modality for the response of the mTOR inhibitor everolimus monotherapy in breast cancer cell lines and in patient-derived cell culture (PDCC) from metastatic breast cancer sites." (PMID 31358767, 2019). "The Akt/AMPK/mTOR pathway was shown to be one of the targets of quercetin in MDA-MB-231 and MDA-MB-435 breast cancer cells." (PMID 31064104, 2019).